FOXA1 (forkhead box A1)
Diseases named in the same sentence as FOXA1 in open-access papers (continued):
Sharing a sentence is not in itself a finding about the gene and the disease.
breast carcinoma (continued). "In breast cancer, a positive correlation between FOXA1 and ER expression has been reported." (PMID 35561288, 2022). "In tamoxifen-resistant ER+ breast cancer, the high level of FOXA1 could be reduced by sorafenib and nilotinib, leading to the re-sensitization of the tamoxifen-resistant cells." (PMID 36012038, 2022). "Similarly, transcription factor FOXA1 is essential in a subset of lung and breast cancers but shows a breast-specific functional interaction with ETS family transcription factor SPDEF." (PMID 35768873, 2022). "Previous results in T47D mammary cancer cells have shown Hormone Control Regions, which include ERbs and PRbs acting in conjunction with FOXA1 and C/EBPa interact with promoters of hormone regulated genes in hormone-responsive TADs and organize the high level folding of the genome." (PMID 35018885, 2022). "Additionally, miR-132-3p has been shown to bind with 3’ UTR of FOXA1 and suppress its expression, thus reducing breast cancer cells proliferation." (PMID 34094972, 2021). "β-catenin gene silencing significantly reduced FOXA1 gene expression in breast cancer cells." (PMID 33669586, 2021). "In MCF-7 breast cancer cells, these regions are bound by FOXA1 and ER, and enriched for H2A.Z and H3K27ac, suggesting that they may function as enhancer elements in HR+ breast cancer tumors." (PMID 34922480, 2021). "Highlighting these genes differentially marked with the broad H3K4me3 domain in MDA-MB-231 cells (SPRY4) and in MCF7 cells (FOXA1 or GATA3) demonstrates the importance of these genes in maintaining the cellular properties of these two different types of breast cancer cells." (PMID 34238359, 2021). "Together these data support inhibiting FOXA1 for breast cancer management." (PMID 34680352, 2021). "It has been recently reported that FOXA1/GRHL2 collaboration could establish a targetable pathway in endocrine therapy-resistant breast cancer, and facilitate depositing H3K4me1 at potential enhancer elements by recruiting the chromatin modifier MLL3." (PMID 34395436, 2021). "First, FOXA1 is a critical determinant of estrogen receptor signaling and is required for cell cycle progression and proliferation of luminal breast cancer, which accounts for the majority of breast cancer diagnoses." (PMID 34680352, 2021). "Given that FOXA1 assists the transcriptional activity of the ER and may be involved cooperatively in the tumorigenesis of breast cancer, the FOXA1-ER axis may also play crucial roles in EMPD development and progression in some cases." (PMID 34436026, 2021). "As ER binding and cell proliferation show a dependency on FOXA1 even in an endocrine-resistant setting, FOXA1 represents an attractive (yet currently undruggable) therapeutic target in breast cancer, with FOXA1 inhibitors potentially also effective where resistance to ER antagonists has emerged." (PMID 33284960, 2021). "Thus, FOXA1 acts as a bona fide pioneering factor to establish ER binding patterns in breast cancer, making FOXA1 a key determinate of hormonal response in this disease." (PMID 34680352, 2021). "Moreover, one study showed that FOXA1 knockdown reduced HER3 gene expression in a panel of breast cancer cell lines, corroborating our results showing that FOXA1 gene silencing reduced HER3 protein expression." (PMID 33669586, 2021). "In addition, FOXA1 plays a central role in almost all ERα-chromatin interactions and gene expression changes in hormone-sensitive and -resistant breast cancer cell lines." (PMID 34215221, 2021). "Thus, hyperactive FOXA1 drives endocrine-resistant breast cancer phenotypes through transcriptional reprogramming." (PMID 34680352, 2021). "Our findings suggest that MAGEA12 may collaborate with FOXA1 to regulate the aggressiveness of breast cancer cells." (PMID 34202157, 2021). "Moreover, FOXA1 expression is more highly correlated with AR than ER expression in breast cancer, suggesting the dual functions of FOXA1 in AR-positive versus ER-positive disease." (PMID 34680352, 2021).
breast carcinoma (continued). "However, in other subsets of breast cancer, including TNBC and endocrine-therapy resistant tumors, FOXA1 is associated with worse clinical outcomes." (PMID 34680352, 2021). "Interestingly, AR agonist treatment in breast cancer models reprograms binding of both FOXA1 and ESR, suggesting some degree of antagonistic function between the androgen and estrogen receptors." (PMID 34227937, 2021). "Regardless of whether NRs can also serve as recruiting factors for FOXA1, the weight of evidence supports FOXA1’s role as a pioneer factor for estrogen signaling in breast cancer." (PMID 34680352, 2021). "GATA3 and FOXA1 are marker genes that define an ESR1-positive breast cancer." (PMID 34395436, 2021). "In addition, when we divided the 70 breast cancer cell lines into those that had high or low FOXA1 expression, we found that EFNA1 expression was significantly higher in the lines with high FOXA1 expression." (PMID 34202157, 2021). "As FOXA1 is known to assist the transcriptional activity of the estrogen receptor (ER) and may work cooperatively in the tumorigenesis of breast cancer, we also performed immunohistochemical staining for ER." (PMID 32235312, 2020). "Moreover, FOXA1 is required not only for maintaining luminal-specific gene expression, but also for suppressing genes specific for basal breast cancer cells." (PMID 32929382, 2020). "In breast cancer, overexpression of FOXA1 correlates with good prognosis in ER+ cases." (PMID 32685483, 2020). "However, in the study of breast cancer and endometrial cancer, it was found that the positive expression of FOXA1 was significantly negatively correlated with the poor prognosis of patients, which plays a role in inhibiting the development of tumors." (PMID 32411194, 2020). "FOXA1-overexpressing cells grow significantly faster than control cells even under fulvestrant treatment, suggesting that increased FOXA1 expression induces cellular tolerance to anti-ER treatment in breast cancer." (PMID 32235312, 2020). "To explore whether super-enhancer-associated lncRNA can also regulate the expression of TFs and be involved in forming CRC, we measured the expression of FOXA1 in breast cancer and lung adenocarcinoma cell lines after knockdown of DSCAM-AS1." (PMID 32929382, 2020). "Conversely, if a target therapy against FOXA1 upregulation in breast cancer is developed, it may be incorporated into PD chemotherapies, which are currently sub-optimal." (PMID 32235312, 2020). "ERα is a master regulator that co-binds with FOXA1 in ER+ breast cancer." (PMID 32929382, 2020). "Similarly, in the medical literature, most publications report a very strong correlation between FOXA1 positivity in breast cancers and the expression of the hormone receptors ER and PR, confirmed by two meta-analyses, AR, and the luminal-A phenotype." (PMID 31888566, 2019). "Our correlation analysis displayed that EYA2 was inversely associated with FOXA1, which further supported the correlation between high EYA2 expression and poor tumor differentiation.ER, PR and HER2 are critical pathological markers in breast cancer." (PMID 30761270, 2019). "Therefore, although the targeting of FOXA1 is proposed as a strategy to treat luminal types of breast cancers, this approach can result in cells reprogramming into more aggressive cancers." (PMID 31013830, 2019). "Forkhead box protein A1 (FOXA1) is a pioneer factor of estrogen receptor α (ER)–chromatin binding and function, yet the role of FOXA1 in breast cancer and the underlying molecular mechanisms have not yet been elucidated." (PMID 31562808, 2019).
breast carcinoma (continued). "In this report, we hypothesized that FOXA1 is a promising candidate as a therapeutic and prognostic target for breast cancer." (PMID 31562808, 2019). "In breast cancer, FOXA1 amplification was a marker of favorable prognosis." (PMID 30819139, 2019). "In human breast cancer, many studies have reported a negative association between FOXA1 and grade in consecutive series of breast cancers, but not in ER-negative breast cancers considered separately." (PMID 31888566, 2019). "In addition, it has prognostic value for breast cancer; FOXA1 expression in ER+ breast cancer is positively correlated with better prognosis." (PMID 31562808, 2019). "Among others, luminal-AR breast cancers highly express the Forkhead box A1 (FOXA1) gene." (PMID 31888566, 2019). "The frequency of FOXA1 positivity in breast cancer ranges from 41.5 to 85.9% of cases." (PMID 31888566, 2019). "FOXA1 is the primary determinant of ER binding and transcriptional activity in breast cancer cells." (PMID 31921620, 2019). "To evaluate whether the expression level of FOXA1 has predictive value for breast cancer prognosis, we used the online survival analysis software Kaplan–Meier plotter." (PMID 31562808, 2019). "To evaluate this hypothesis, we used a bioinformatics approach to determine the expression and prognostic value of FOXA1 in breast cancer overall and in its subtypes." (PMID 31562808, 2019). "Methylation of APC, FOXA1, and RASSF1A in cell free DNA served as a best performing cassette in terms of diagnostic and prognostic value, revealing a sensitivity, specificity and accuracy over 70% suggesting its putative utility in management of breast cancer." (PMID 31608277, 2019). "By contrast, inhibition of the expression of FOXA1 in luminal breast cancer cell lines, such as MCF7 and T47D, and SKBR3 not only leads to silencing of luminal genes but also causes the induction of basal genes and enhanced cell migration and invasion, which represent the basal phenotype." (PMID 31013830, 2019). "Furthermore, FOXA1 has been shown to be a pioneer factor in steroid hormone signaling in breast cancer- and prostate cancer-derived cell lines." (PMID 30978209, 2019). "The objectives of this study were to describe AR and FOXA1 expressions in feline mammary carcinomas (FMCs), their prognostic value, and if their coexpression could define a “luminal-AR” subtype of triple-negative mammary carcinomas in cats." (PMID 31888566, 2019). "Expression of FOXA1 in luminal cancer was much higher than that in basal-like breast cancer." (PMID 31921620, 2019). "Furthermore, FOXA1, GATA3, ESR1 and SPDEF are reported as master regulators in FGFR2 signaling and breast cancer risk in ER+ cells." (PMID 29741575, 2018). "FOXA1 is overexpressed in hormone-dependent cancers, including breast cancer." (PMID 29864144, 2018). "These particular properties support the idea that FOXA1 could be an attractive target of ER positive breast cancer especially in endocrine resistant context." (PMID 30572598, 2018). "Hence, in this study, we aimed to investigate which proteins can control FOXA1 in different breast cancer cell lines." (PMID 30572598, 2018). "Here in this study, we aimed to identify which are the proteins that could potentially control FOXA1 function in breast cancer cell lines expressing different molecular markers." (PMID 30572598, 2018). "In contrast to most other mouse models of human breast cancer, the resulting tumors are ovary-dependent and have uniformly high levels of estrogen receptor (ER)-α and progesterone receptor (PR), as well as elevated transcription of Forkhead box A1 (FoxA1)." (PMID 28865492, 2017). "Using a combined gene set consisting of both groups of genes, we found that promoter regions with BRCA1 mutation-associated R-loops are enriched with binding sites for breast cancer-related transcription factors, such as GATA3 and FOXA1 in LP cells and SMAD2/4 and STAT6 in ML cells." (PMID 28649985, 2017).
breast carcinoma (continued). "Similarly, the estrogen receptor (ER) is targeted by tamoxifen for the treatment of ER positive breast cancer, and co-operates with the FOXA1 TF to drive breast cancer progression." (PMID 29312534, 2017). "Indeed, insulin-like growth factor-I was reported to increase the stability of FoxA1 protein in MCF7 breast cancer cell line via Akt pathway." (PMID 28436428, 2017). "Interestingly, the EZH2 methyltransferase inhibitor, GSK126, promotes FOXA1 expression and inhibits breast cancer growth via cooperation with BRCA1." (PMID 28264478, 2017). "In this study, we showed that expression of the pro-inflammatory cytokine IL-20 was regulated by a transcriptional complex composed of the transcription factors ER(α), GATA3, and FOXA1 and the transcriptional elongation factor Ell3 in ER(+) breast cancer cells." (PMID 28514748, 2017). "129:Stat1−/− mammary carcinomas are exclusively FoxA1+ as well as ER+ and PR+." (PMID 28865492, 2017). "Therefore, possible therapeutic strategies such as anti-androgens should be examined considering the AR, FOXA1, and ER status in breast cancer patients." (PMID 29137314, 2017). "In addition, western blot analysis indicated that FOXA1 protein expression was restricted to the ER+ breast cancer cell lines analyzed, whereas OCT1 was more widely expressed." (PMID 27640304, 2016). "An in vitro study confirmed this role of FoxA1 in ER-negative, AR-positive breast cancer cells." (PMID 26797644, 2016). "In conclusion, our analysis of the effect of potential modulators of SPDEF and FOXA1 activity in ER+ breast cancer suggests that MINDy and other such computational tools have the power to identify valid modulators of TF activity that warrants further follow-up work." (PMID 27997592, 2016). "FOXA1 is also a pioneer factor for AR DNA binding in prostate cancer cells and this function may be preserved in breast cancer expressing AR." (PMID 26797644, 2016). "FOXA1 and GATA3 on the otherhand are mutated in primary breast cancer." (PMID 26884552, 2016). "FOXA1 is the best-studied and will be used as an example of how pioneer factors shape the landscape of SNRs in breast cancer and thus may modulate their influence on EMT." (PMID 26797644, 2016). "We have identified 36 TFs whose regulons are significantly enriched for genes associated with breast cancer risk loci (termed “risk TFs”), and four of these risk TFs (ESR1, FOXA1, GATA3 and SPDEF) have been identified as MRs of FGFR2-mediated risk in breast cancer." (PMID 27997592, 2016). "We performed RIME of FOXA1 in MCF-7 breast cancer cells to identify endogenous FOXA1 interactors." (PMID 27926873, 2016). "We sought to discover proteins that interact with FOXA1 in ER-positive (ER+) breast cancer cells by performing FOXA1 RIME (rapid immunoprecipitation mass spectrometry of endogenous proteins), an unbiased proteomic method that permits discovery of protein networks." (PMID 27926873, 2016). "FOXA1 was shown to be required for all ERbinding sites in models of ER+ breast cancer, and was also shown to berequired for ER binding and growth of endocrine-resistant breast cancer cell linemodels." (PMID 26884552, 2016). "The concept that NANOG may reprogram somatic cancer cells via converging on lineage master TFs such as AR/FOXA1 is likely applicable to the NANOG functions in other tumor systems such as breast cancer." (PMID 27867534, 2016). "Our findings that MLL3 and FOXA1 physically interact in breast cancer cells implies that FOXA1 may be able to directly recruit the enzyme that can add methyl groups to the H3K4 residue." (PMID 27926873, 2016). "Knockdown of BRCA1 resulted in the downregulation of FOXA1 expression and enhancement of FOXA1 promoter methylation in MCF-7 breast cancer cells, whereas the reconstitution of BRCA1 in Brca1-deficent mouse mammary epithelial cells (MMECs) promoted Foxa1 expression and methylation." (PMID 25531315, 2015).
breast carcinoma (continued). "FOXA1 expression correlates with the breast cancer luminal subtype and patient survival." (PMID 25531315, 2015). "Functional genomic annotation using data derived from breast cancer cell-line models indicates that these SNPs localise to putative enhancer elements that bind known drivers of hormone-dependent breast cancer, including ER-α, FOXA1 and GATA-3." (PMID 25652398, 2015). "In ER- breast cancers, FOXA1 may promote androgen signaling and may contribute to the development of resistance to anti-androgen therapy." (PMID 26618778, 2015). "Moreover, FOXA1 alters the pattern of ER binding in ‘poor outcome/metastatic’ ER+ breast cancer from that found in ER+ ‘good outcome’ breast cancer." (PMID 25632947, 2015). "In breast cancer cells, FOXA1 and FOXO3a can regulate the function of ERα via their FOX domains, and since FOXK2 also contains a conserved FOX domain, we speculated that it too may interact with ERα." (PMID 25740706, 2015). "Firstly, the transcription factor FOXA1 (forkhead box protein A1) that is known to be strongly involved in breast cancer was removed by the NCA algorithm in 84 % (84/100) of the configurations (it was retained 100 % by the ISNCA), loosing the ability to study its effect on the network." (PMID 26537518, 2015). "In addition, FOXA1 and GATA3 are frequently targeted by mutations in breast cancer, while PBX1 is rarely affected by somatic mutations (V117M and H425N, 2 out of 892 patients)." (PMID 26215677, 2015). "Recent studies have identified several genes that under long-range regulation during breast cancer progression, including those encoding transcription factors such as ER, PR, AP1, AP2, FoxA1, GATA3, architectural components such as cohesion and SATB1, coactivators such as p300/CBP and SRC1-3." (PMID 26355959, 2015). "Apart from the fact that the role of the PPARG/RXRA heterodimer in urothelial cancer is exchanged with the ESR1 hormone receptor in breast cancer, the key transcription factors FOXA1 and GATA3 are downregulated in the basal/SCC-like subtypes of both tumor types." (PMID 26008846, 2015). "The present finding suggests that FOXA1 involvement in ERα regulation might be different in endometrial cancer compared to what is found in breast cancer." (PMID 24849812, 2014). "As FOXA1 is shown to be important for ERα-chromatin interactions in breast cancer, we further investigated whether FOXA1 related gene expression resembles ERα regulated gene expression in endometrial cancer." (PMID 24849812, 2014). "Our study defines the mechanism by which MLL1 nucleates histone H3K4 methylation marks in CpG-enriched regions to maintain permissive chromatin architecture and allow FOXA1 and estrogen receptor α binding to transcriptional regulatory sites in breast cancer cells." (PMID 24288367, 2014). "The FoxA1 protein is known to cooperatively interact with estrogen receptor in breast cancer cells." (PMID 24736605, 2014). "However, in hepatocellular carcinoma, pancreatic, and estrogen receptor (ER)-positive breast cancer, FOXA1 has been reported to have a tumor-suppressive function." (PMID 24512546, 2014). "Moreover, the interaction between TLE3 and FoxA1 was demonstrated in mouse liver cells and in our breast cancer cells." (PMID 25223786, 2014). "FOXA1 has previously been shown to be a pioneer factor for ER in breast cancer." (PMID 24849812, 2014). "In breast cancer cells FOXA1 has been shown to be necessary for estrogen response." (PMID 24849812, 2014). "In breast cancer cells, FoxA1 plays an important role in the estrogen signaling pathway." (PMID 25223786, 2014). "The current hypothesis regarding the role of FOXA1 in breast cancer is that FOXA1 is capable of mediating a reprogramming of the ERα binding site." (PMID 24265722, 2013). "In breast cancer, FOXA1 expression is highly correlated with ER(+), PR(+) and endocrine signaling, and may have a prognostic value in ER(-) tumors." (PMID 23663520, 2013).